CD96 (CD96 molecule)
Diseases named in the same sentence as CD96 in open-access papers (continued):
Sharing a sentence is not in itself a finding about the gene and the disease.
melanoma (continued). "HD and melanoma patient sera were tested for immunosuppressive factors MICA, NT5E/CD73 and tactile/CD96, as well as perforin, which is released by cytotoxic NK and T cells and is a surrogate biomarker for in vivo cytolytic activity of these effectors." (PMID 30761123, 2019). "Further, combining the blockade of CD96 and TIGIT could enhance the inhibitory effect on lung metastasis of melanoma cells." (PMID 36674817, 2023). "However, CD96−/− mice revealed an inhibitory role for CD96, since its absence improves IFN-γ production and reduces melanoma metastasis formation in the lungs." (PMID 37760586, 2023). "Relative to T cells, the correlation between CD96 and NK cell-related genes is more infrequent despite being strong for specific indications such as HCC, head and neck squamous cell carcinoma (HNSCC), stomach adenocarcinoma, and melanoma." (PMID 35812451, 2022). "Immunohistochemistry studies have situated CD96 as a marker of poor prognosis and immune exhaustion in HCC as well as in other cancer types like melanoma, gastric cancer, and pancreatic cancer; some of which also identified TIGIT as a negative prognostic marker." (PMID 33498698, 2021). "Together, the effect of the absence of CD96 is a strong suppression of melanoma lung metastasis." (PMID 38893071, 2024). "The absence of CD96-signaling in mice resulted in improved resistance to melanoma metastasis, and it will be interesting to discover how expression of this molecule specifically on ILC2s may regulate immunity." (PMID 31024538, 2019). "Given that the axis is active in immune surveillance of both melanoma and ovarian tumour cells, we established that platelet cloaked tumour cells, activated platelets and platelet releasate all function to suppress expression of CD226 and CD96 on the NK cell surface." (PMID 30908480, 2019). "The immune and inflammatory response node contained 99 proteins and genes directly involved in the immune response such as interleukins and chemokines; T lymphocyte markers such as CD96, TLR8, CD80; or CCR5, beta-2-microglobulin (B2M) or absent in melanoma 2 (AIM2)." (PMID 37686682, 2023). "Here, we show that, after intravenous injection with sCD155-producing B16/BL6 melanoma, the numbers of tumor colonies in wild-type (WT), TIGIT knock-out (KO), or CD96 KO mice, but not DNAM-1 KO mice, were greater than after injection with parental B16/BL6 melanoma." (PMID 32040157, 2020).
hepatocellular carcinoma (18 papers, 2019 to 2024). A malignant tumor that arises from hepatocytes. "In patients with hepatocellular carcinomas, a high expression of CD96 and CD155 was associated with decreased survival." (PMID 37046787, 2023). "Higher CD96+ NK cell levels, with distinctive exhaustion and cytokine secretion, have been found in intra-tumoral sites of hepatocellular carcinoma (HCC) patients or ovarian cancer ascites cases." (PMID 39339180, 2024). "Taken together, these findings suggest that CD96 can negatively regulate tumor immunity in hepatocellular carcinoma through lymphocytes such as CD8+ T cells and NK cells." (PMID 36674817, 2023). "Intratumoral NK cells in hepatocellular carcinomas showed a higher CD96 expression compared to the peritumoral tissue." (PMID 37046787, 2023). "Bioinformatics-based analysis of CD96 gene expression in the tissues of patients with hepatocellular carcinoma revealed an increased expression of CD96, suggesting the potential role of CD96 in assisting tumor cells to evade the immune system." (PMID 36674817, 2023). "In hepatocellular carcinoma, CD96+ NK cells have been reported to be functionally exhausted with increased expression of inhibitory cytokines and impaired degranulation and effector cytokine production." (PMID 35769718, 2022). "In hepatocellular carcinoma patients, the percentage and intensity of CD96 on NK cells, as well as the numbers of CD96+ NK cells, were higher in tumor-infiltrating NK cells compared with NK cells from peri-tumoral tissues." (PMID 33946954, 2021). "In hepatocellular carcinoma, patients with higher percentages of intra-tumoral CD96+ NK cells show reduced disease-free survival." (PMID 34503073, 2021). "Functionally exhausted CD96+ NK cells were significantly increased in the tumor tissues of patients with worse prognosis of hepatocellular carcinoma." (PMID 33946954, 2021). "Mechanistically, TGF-β1 appears to sustain CD96 expression on NK cells from hepatocellular carcinoma patients, further emphasizing its role in promoting NK cell exhaustion in the TME." (PMID 32153582, 2020). "Furthermore, a significant correlation between immune evasion and CD96 in hepatocellular carcinoma tissues with high NK cell infiltration has been demonstrated." (PMID 36674817, 2023). "Moreover, CD96 can be used as a potential prognostic marker to predict survival in patients with hepatocellular carcinoma." (PMID 36674817, 2023). "Furthermore, in the liver of hepatocellular carcinoma patients, NK cells from intra-tumoral regions express higher level of CD96 compared to NK cells from peritumoral regions." (PMID 34503073, 2021). "In addition, a study noted an elevated proportion and number of CD96+CD56dim NK cells in hepatocellular carcinoma tissues, and these NK cells were functionally exhausted with impaired IFN-γ and TNF-α productions." (PMID 31681269, 2019). "CD96 has been shown to be a marker for NK cell exhaustion in patients with hepatocellular carcinoma (HCC) and to limit antitumor functions of NK cells in mice." (PMID 36845105, 2023). "CD96+ NK cells are significantly increased in the intra-tumor tissues of hepatocellular carcinoma (HCC)." (PMID 36291830, 2022). "Hepatocellular carcinoma (HCC) patients with high expression level of CD96 within tumor are strongly correlated with deteriorating disease situations and shorter disease-free survival and OS times." (PMID 32695752, 2020). "Patients with hepatocellular carcinoma that present reduced disease-free survival have dysfunctional (exhausted) TINK with a higher frequency of CD96+ cells and increased expression of CD96, but blockade of CD96 restores NK cell-mediated effector functions." (PMID 34394116, 2021). "Patients with hepatocellular cancer who exhibit decreased disease‐free survival have malfunctioning (exhausted) TINK cells with elevated CD96 expression; nevertheless, NK cell‐mediated effector capabilities are restored when CD96 is blocked." (PMID 38882209, 2024).
hepatocellular carcinoma (continued). "However, very few studies go into details about the mechanisms by which CD96 regulates the functions of CD8+ T cells as well as NK cells and contributes to immunity in hepatocellular carcinoma." (PMID 36674817, 2023). "A higher expression of the immune suppressive checkpoints CD96, PD-1, and TIGIT is seen in CD49a+ NK cells, with the number of CD49a+ NK cells positively corelated with the presence of malignant disease and a poor prognosis in patients with hepatocellular carcinoma." (PMID 36674817, 2023).
leukemia (18 papers, 2013 to 2024). A malignant (clonal) hematologic disorder, involving hematopoietic stem cells and characterized by the presence of primitive or atypical myeloid or lymphoid cells in the bone marrow and the blood. "A recent study showed that the deletion of CD96 in human T cells is associated with increased leukemia cell-killing activity in vitro." (PMID 37046787, 2023). "This suggests that CD96+ leukemia patients are more prone to relapse postchemotherapy, indicating CD96 as a potential new prognostic marker." (PMID 39445003, 2024). "Among them, ICG is used as a photosensitizer for leukemia PDT and specifically targets the surface molecules CD117 or CD96 of leukemia stem cells through a bio-conjugation method." (PMID 37353849, 2023). "Here, we demonstrate that CRISPR/Cas9-based deletion of CD96 in human T cells enhanced their killing of leukemia cells in vitro." (PMID 36672244, 2023). "In vivo studies have shown that CD123 and CD96 are highly expressed on the membrane of LSCs, whereas they are weakly expressed on the surface of HSCs and are also involved in the development of leukemia." (PMID 36358676, 2022). "CD96 is a specific marker of leukemia stem cells in human AML, which is a good candidate target for targeting LSC." (PMID 34659343, 2021). "The protein profile of these sEV is enriched in leukemia-associated antigens (LAAs), such as CD34, CD123, CD96, CLL-1, suggesting these are leukemia blast-derived sEVs." (PMID 34296216, 2021). "We next compared expression differences of CD96 mRNA in cancers and normal tissues using Oncomine database, and found it expressed at relatively higher levels in brain cancer, breast cancer, renal cancer, and leukemia than in normal tissues." (PMID 33680972, 2021). "CD96 has also been described as a leukemia stem cell marker in AML." (PMID 24959420, 2014). "The CD96 signaling pathway has remained fairly unclear in solid tumors, although it has been reported to act as a CSC marker in leukemia." (PMID 36581470, 2023). "Using a novel bioconjugation approach to specifically target CD117 or CD96, surface features enhanced on leukemia stem cells, in vitro ICG-CPSNP PDT of a human leukemia samples were dramatically improved." (PMID 30782173, 2019). "Antigens expressed on leukemia blasts or preferentially expressed on leukemia stem cells including CD33, CD45, CD96, CD123, CD135, CLL-1 and T cell immunoglobulin mucin-3 (TIM-3) represent potential targets for antibody-based therapy in AML." (PMID 28018601, 2016). "Several studies have showed that the aberrant expression of specific markers on the cell surface of leukemia progenitors is characteristic for LIC, differentiating them from their normal counterparts, including CD90, CD123, CLL-1, CD96, CD47, Tim3 and so on." (PMID 24517186, 2013). "CD96 is highly expressed in acute myeloid leukemia (AML), T-cell acute lymphoblastic leukemia (T-ALL), and myelodysplastic syndromes and has been proposed as a cancer stem cell marker for leukemia." (PMID 37312878, 2023). "Thus, the established markers of leukemia stem cells such as CD123 and CD96 were determined." (PMID 34504869, 2021). "Spearman’s rank tests showed that the mRNA expression of SMPDL3B was positively correlated with the mRNA expression of CD123, CD96, and CD25 in 151 AML patients, indicating that SMPDL3B may regulate myeloid leukemia development via promoting self-renewal of leukemia stem cells." (PMID 34504869, 2021).
breast carcinoma (17 papers, 2013 to 2025). "Here, we evaluated the CD96+ cell subpopulations among human breast cancer (BC) cells and explored their function and underlying molecular mechanisms of action to explore new targets for tumor therapy." (PMID 36581470, 2023). "CD96 expressed in tumor cells is correlated with poor long‐term prognosis in breast cancer patients." (PMID 36581470, 2023). "The CD96+ breast cancer cells revealed cancer stem cell characteristics and showed increased resistance to chemotherapy." (PMID 37046787, 2023). "The CD96+ cancer cell subpopulations exhibit features of both breast cancer stem cells and chemoresistance." (PMID 36581470, 2023). "Here, it is found that CD96 is frequently expressed in tumor cells from clinical breast cancer samples and is correlated with poor long‐term prognosis in these patients." (PMID 36581470, 2023). "Blocking of CD96 in an immunocompromised xenotransplant mouse model of human breast cancer cells showed reduced tumor growth and increased apoptosis." (PMID 37046787, 2023). "Survival analysis indicated the increased expression of CD79A and CD96 was significantly associated with favorable relapse-free survival (RFS), overall survival (OS) in breast cancer." (PMID 34526986, 2021). "Database analyses including the Oncomine and TCGA gene expression database show a high expression of CD96 in brain cancer, breast cancer, head-and-neck squamous cell carcinoma (HNSCC), and other malignant diseases but a low expression in lung cancer, rectal cancer, and others." (PMID 37046787, 2023). "Meanwhile, CD96 was also low expressed in several cancers, such as breast cancer and skin melanoma." (PMID 33680972, 2021). "Additionally, CD226 and CD96 upregulation was observed on NK cells of relapse free breast cancer patients and CD226 was found to be decreased on anergic NK cells associated with lung cancer." (PMID 30908480, 2019). "Unsupervised clustering performed on the filtered gene set and based on DNAM1, NCR3(NKp30), CD96 and Class I–Restricted T-cell–Associated Molecule (CRTAM) expression signatures was able to spontaneously segregate the breast cancer patients in two distinct cohorts." (PMID 23758773, 2013). "Therefore, blocking CD155-TIGIT or CD96 signalling could enhance anti-tumour immune cell function, making it a potential marker for immunotherapy in breast cancer." (PMID 37519808, 2023). "In addition to immune cells, a recent study revealed CD96 expression in human breast cancer cells." (PMID 37046787, 2023). "Mechanistically, CD96 enhances mitochondrial fatty acid β‐oxidation via the CD155‐CD96‐Src‐Stat3‐Opa1 pathway, which subsequently promotes chemoresistance in breast cancer stem cells." (PMID 36581470, 2023). "This indicates that CD96 signaling can be initiated by tumor cells and that CD155–CD96 interaction contributes to chemoresistance in breast cancer cells independent of immune cells." (PMID 37046787, 2023). "Our findings revealed a significant expression of CD96 in TME NK cells in lymph nodes, indicating that CD96 could also be a potential target for controlling breast cancer metastasis in the early stage." (PMID 36148946, 2022).
acute myeloid leukemia (9 papers, 2012 to 2023). Acute myeloid leukemia (AML) is a group of neoplasms arising from precursor cells committed to the myeloid cell-line differentiation. "A high level of CD96 has been reported in myelodysplastic syndrome, acute myeloid leukemia (AML), and T-cell acute lymphoblastic leukemia (T-ALL)." (PMID 38003255, 2023). "CD96 expression was found to be restricted to T cells and NK cells, and is ectopically expressed by acute myeloid leukemia (AML) cells." (PMID 35406483, 2022). "We showed that genetic ablation of CD96 in human T cells enabled these cells to kill chronic myeloid leukemia (CML) cells and a subset of acute myeloid leukemia (AML) cells more efficiently in vitro." (PMID 36672244, 2023). "CD96, a cell surface antigen recently described to be preferentially expressed on acute myeloid leukemia (AML) leukemic stem cells (LSC) may represent an interesting target structure for the development of antibody-based therapeutic approaches." (PMID 22879978, 2012). "CD96 is a promising candidate as a leukemic stem cell (LSC)-specific antigen and is expressed on the majority of CD34+CD38− Acute myeloid leukemia (AML) cells, whereas only a few cells in the normal Hematopoietic stem cell (HSC)-enriched population express CD96 weakly." (PMID 22634835, 2012).
pancreatic cancer (9 papers, 2016 to 2024). "Supporting a role for CD226 and CD96 in the context of tumour evasion, a study of patients with pancreatic cancer demonstrated that CD226+CD96+ NK cells are deficient in patients versus healthy controls, while TIGIT was not altered." (PMID 30908480, 2019). "In humans, a significantly decreased percentage of CD96+ NK cells in pancreatic cancer patients and associations of this decreased percentage with lymph node metastasis and tumor histological grade were observed, suggesting a possible protective role for CD96+ NK cells in pancreatic cancer." (PMID 31681269, 2019). "The percentage of DNAM1+ and CD96+ NK cells is significantly lower in pancreatic cancer patients than in healthy controls, and reduced percentages of DNAM1+ and CD96+ NK cells are associated with tumor histologic grade and lymph node metastasis." (PMID 39156900, 2024). "In pancreatic cancer patients, a decreased proportion of CD96+ NK cells was found in the peripheral blood compared with the healthy controls." (PMID 37046787, 2023). "In the peripheral blood of pancreatic cancer patients, a significant decrease in CD96+ NK cells was shown in the flow cytometry." (PMID 37046787, 2023). "There seems to be a dysregulation of the TIGIT/CD96/CD226/CD155 pathway involving NK cells in pancreatic cancer patients, warranting further in vitro and in vivo evaluation." (PMID 32117298, 2020). "However, TIGIT expression was found to be similar between pancreatic cancer patients and healthy controls, while CD226 and CD96 were downregulated." (PMID 32117298, 2020).
fibrosarcoma (7 papers, 2014 to 2023). A malignant mesenchymal fibroblastic neoplasm affecting the soft tissue and bone. "In support of this notion, combined TIGIT and CD96 blockade has shown increased efficacy at preventing tumor growth via a CD8+ T cell-mediated mechanism in a mouse fibrosarcoma model in comparison to either antibody alone." (PMID 33013915, 2020).
glioblastoma (6 papers, 2020 to 2024). The most malignant astrocytic tumor (WHO grade IV). "Compared to other pathological subsets (namely oligodendroglioma, oligoastrocytoma, and astrocytoma), CD96 expression was relatively upregulated in glioblastoma." (PMID 32695752, 2020). "We also detected the prognostic value of CD96 expression in glioblastoma (GBM)." (PMID 32612110, 2020). "Subsequent immune infiltration analysis showed that CD96 was positively correlated with infiltrating levels of CD4 + T and CD8 + T cells, macrophages, neutrophils, and DCs in glioblastoma multiforme and low-grade glioma." (PMID 32695752, 2020).
acute lymphoblastic leukemia (5 papers, 2022 to 2024). Leukemia with an acute onset, characterized by the presence of lymphoblasts in the bone marrow and the peripheral blood. "Likewise, it was shown that AML patients had a higher percentage of CD96 than those with acute lymphoblastic leukemia (ALL), with the percentage of CD96 in each subgroup of AML: myeloblasts/promyelocites > granular myeloblasts > monoblasts." (PMID 36674817, 2023). "CD96 (T-cell activation, increased late expression [TACTILE]) was first identified as an orphan receptor on AML and T-cell acute lymphoblastic leukemia (T-ALL) cell lines." (PMID 35812451, 2022).
cervical cancer (5 papers, 2022 to 2024). A primary or metastatic malignant neoplasm involving the cervix. "Blockade of BTLA and CD96 is promising for use in combination with PD1 blockade in the treatment of cervical cancer, as targeting the ICI CD96 overcomes PD1 blockade resistance by boosting CD8+ T-cell function." (PMID 38928307, 2024). "CD8+ and CD96+ T cells in cervical cancer patients not responding to anti-PD1 ICI treatment often showed a co-expression of CD96 and PD1." (PMID 37046787, 2023). "In cervical cancer, CD96 expression on the CD8+ T cells of patients not responding to anti-PD1 immunotherapy was increased." (PMID 37046787, 2023).
colorectal cancer (4 papers, 2020 to 2023). A primary or metastatic malignant neoplasm that affects the colon or rectum. "CD96 deficiency reduced the frequencies of NUR77-, T-bet-, TNFα- and IFNγ-expressing tumor-specific CD8+ T cells in a mouse model of colorectal carcinoma, suggesting CD96 co-stimulated rather than inhibited effector T cell anti-tumor responses." (PMID 36672244, 2023). "This cell state displayed activation (CXCL13) and exhaustion (LAG3, HAVCR2, CD96) markers, which may account for their participation in the immune checkpoint inhibitor sensitivity of MSI-H colorectal cancers." (PMID 35538548, 2022).
gastric cancer (4 papers, 2021 to 2025). A primary or metastatic malignant neoplasm involving the stomach. "In gastric cancer, high CD96 infiltration was associated with an inferior prognosis." (PMID 37046787, 2023).